PCDH9 (protocadherin 9)
Diseases named in the same sentence as PCDH9 in open-access papers (continued):
Sharing a sentence is not in itself a finding about the gene and the disease.
epilepsy (2 papers, 2021 to 2024). A brain disorder characterized by episodes of abnormally increased neuronal discharge resulting in transient episodes of sensory or motor neurological dysfunction, or psychic dysfunction. "We discovered the combinatorial expression of Protocadherin-19(Pcdh19), a protein involved inPCDH19-clustering epilepsy, with Pcdh1, Pcdh9 or Cadherin 13 (Cdh13) in excitatory neurons." (PMID 38629124, 2024). "Other genes with CNV losses that have an indirect relation to epilepsy are RYR3, CDH13, PCDH9, and LRRC55." (PMID 33557955, 2021).
leukemia (2 papers, 2017). A malignant (clonal) hematologic disorder, involving hematopoietic stem cells and characterized by the presence of primitive or atypical myeloid or lymphoid cells in the bone marrow and the blood. "The angiogenesis is another process getting disorder in cancerous states (PLXNC1 and PCDH9 genes in the list of leukemia)." (PMID 29563929, 2017). "The process of contact and intracellular connections and cellular migration (PLXNC1 and PCDH9 genes in leukemia) and other processes such as activating EGFR and SMAD pathways were the other processes that selected genes in this project were involved to control and regulate the processes." (PMID 29563929, 2017). "Using RNA sequencing, we found that genes associated with AML subtypes, such as RYR3, RHAG, PCDH9, ANK1, ADAMTS3, and DLC1, were significantly up-regulated in the leukemia cells of two responders, but not in the 3 non-responders." (PMID 28900115, 2017). "Also, key genes of leukemia data set were BAG4, ANKHD1-EIF4EBP3, PLXNC1, and PCDH9 genes, and the accuracy and precision were 100 and 95.24, respectively." (PMID 29563929, 2017).
melanoma (2 papers, 2022). A malignant, usually aggressive tumor composed of atypical, neoplastic melanocytes. "We delved into the biological function of PCDH9 in melanoma and found that it played the role of the tumor suppressor gene." (PMID 36387162, 2022). "PCDH9 was poorly expressed in human melanoma tissues, and overexpression of PCDH9 inhibited melanoma progression." (PMID 36387162, 2022). "Overexpressed PCDH9 suppressed melanoma cells, and PCDH9 can be considered as an independent prognostic factor for melanoma; even re-expression of PCDH9 can serve as a potential therapeutic strategy for melanoma treatment." (PMID 36452505, 2022). "As time passed, the viability of melanoma cells trended to stabilize, but the inhibition rate of cell proliferation in overexpressed PCDH9 groups was higher than that in the blank/control groups, and the differences were significant at 24, 48, 72, and 96 h." (PMID 36387162, 2022). "In summary, PCDH9 can be considered as an independent prognostic factor for melanoma, and re-expression of PCDH9 can serve as a potential therapeutic strategy for melanoma treatment." (PMID 36452505, 2022). "The findings indicated that PCDH9 functioned as a tumor suppressor gene in melanoma development, and circ_0084043 is proved to be an oncogene." (PMID 36387162, 2022). "We found that PCDH9 was closely related to the prognosis of patients with melanoma, and it was lowly expressed in human MM tissues." (PMID 36387162, 2022). "The overexpression of PCDH9 promoted the apoptosis in both melanoma cells, whereas the interfered PCDH9 barely influenced the apoptosis in both cell lines." (PMID 36452505, 2022). "Certain assays (cell viability, apoptosis and cell cycle assays, and PCR) were performed to explore the alteration influence of PCDH9 in melanoma cells." (PMID 36452505, 2022). "According to previous studies of ours and others, the main objective of this investigation is to clarify the role of PCDH9 in melanoma and to provide evidence and a novel possible treatment of melanoma." (PMID 36452505, 2022). "Specimen investigations of IHC assay exhibited lower PCDH9 expressions in malignant melanoma specimens than in benign nevus tissue or/and normal skin." (PMID 36452505, 2022). "In conclusion, PCDH9, which is regulated by the circ 0084043-miR-134-5p axis, can suppress malignant biological behavior in melanoma and influence the expression levels of Pyk2, RAC1, Cyclin D1, MMP2, and MMP9." (PMID 36387162, 2022). "The immunohistochemical (IHC) analysis and bioinformatics mining exhibited the suppression of PCDH9 on melanoma." (PMID 36452505, 2022). "The effects of PCDH9 on melanoma cells were assessed in terms of alteration of PCDH9 such as cell viability, apoptosis, cell cycle, and wound-healing assay." (PMID 36452505, 2022). "As time passed, the viability of melanoma cells tended to stabilize, but PCDH9-overexpressed groups had less viable cells than control groups in different durations, and the differences between PCDH9 and control groups were significant (24, 48, 72, and 96 h)." (PMID 36452505, 2022). "Our results suggested that the effect of PCDH9 on melanoma by RAC1 suppresses RAC1-dependent NADPH oxidase activity to decrease ROS generation and ROS-induced angiogenesis." (PMID 36452505, 2022). "In the current study, the expressions of Pyk2 and RAC1 in melanoma cells were significantly affected by the alteration of PCDH9." (PMID 36387162, 2022). "To further identify the anticarcinogenic of PCDH9 in melanoma, we established the subcutaneous xenograft tumor model using nude mice." (PMID 36387162, 2022). "This study investigated whether the circ_0084043-miR-134-5p axis regulates the antitumor effect of protocadherin 9 (PCDH9) in melanoma." (PMID 36387162, 2022). "The overexpression of PCDH9 reduced the viability of melanoma cells." (PMID 36452505, 2022). "To conclude, the increase of PCDH9 could suppress melanoma cells by observing the deregulation of MMP2, MMP9, and RAC1." (PMID 36452505, 2022).
melanoma (continued). "The overexpression of PCDH9 reduced the proliferation of melanoma cells." (PMID 36387162, 2022). "In vivo, PCDH9 overexpression inhibited melanoma tumor growth, but PCDH9 KD promoted it." (PMID 36387162, 2022). "We further observed the effect of KD circ_0084043 on the malignant behavior of melanoma and studied whether circ_0084043 sponged miR-134-5p and regulated PCDH9." (PMID 36387162, 2022). "IHC showed lower PCDH9 expression in melanoma tissue with main expression in cytoplasm." (PMID 36452505, 2022). "IHC results showed that the positive percentage of PCDH9 expression was lower in human melanoma tissue than in normal skin or/and pigmented nevus tissue; in addition, PCDH9 was mainly expressed in the cytoplasm, whereas a small amount was expressed in the nuclei." (PMID 36452505, 2022). "Hence, MMP2 and MMP9 were chosen as tumorigenic indicators to exhibit the correlation between PCDH9 and melanoma suppression." (PMID 36452505, 2022). "In vivo, overexpression of PCDH9 inhibited melanoma tumor growth, but KD of PCDH9 promoted it." (PMID 36387162, 2022). "The expression of PCDH9 significantly affected the apoptosis of melanoma cells as well." (PMID 36387162, 2022). "The positive percentage of PCDH9 expression in normal skin, pigmented nevus, and melanoma tissues." (PMID 36387162, 2022). "All the findings allow us to recognize that PCDH9 may be a key molecule in the malignant transformation of the melanocyte and the progression of melanoma." (PMID 36387162, 2022). "Together, our results reveal that the alteration of PCDH9 expression could suppress melanoma proliferation and cell migration." (PMID 36452505, 2022). "To conclude, overexpressing PCDH9 could significantly inhibit melanoma cell migration by decreasing cell viability and increasing apoptosis." (PMID 36387162, 2022). "The expression of MMP2 is a prognostic marker for patients with MM that could independently predict patient survival, and its expression has been related to the poorer survival of patients with melanoma, consistent with varied PCDH9 expression in melanoma cells." (PMID 36387162, 2022). "Hence, RAC1 is a good indicator to reflect the effect of PCDH9 on melanoma." (PMID 36452505, 2022). "The results revealed that PCDH9 may affect melanoma cells by different ways." (PMID 36452505, 2022). "In the context of SOCE role, we speculate that the binding between PCDH9 and calcium ion can increase the adhesion of melanocytes, whereas the adhesion of non-native cells increases in lower expressions of PCDH9 that can enhance the migration of melanoma cells." (PMID 36452505, 2022). "Therefore, we have chosen MMP2, MMP9, Pyk2, and Cyclin D1 as tumor metastasis indicators to explore the mechanism of how PCDH9 and RAC1 act on melanoma." (PMID 36387162, 2022). "A positive percentage of PCDH9 was expressed in normal skin or/and pigmented nevus tissue but only 23.3% (7 of 30) in melanoma tissue, which was lower than that in non-tumor tissue." (PMID 36452505, 2022). "PCDH9 was 100% expressed in normal skin (45/45) or/and pigmented nevus tissue (30/30), whereas only 23.3% (7/30) in melanoma tissue, which was lower than non-tumor tissue." (PMID 36387162, 2022). "However, the alteration of PCDH9 expression did not affect melanoma cell regulation in a significant manner (p > 0.05)." (PMID 36452505, 2022). "Increase of PCDH9 could suppress melanoma cells and inhibit migration but not exert significant effects on cell cycle." (PMID 36452505, 2022). "Bioinformatics technologies have been applied to screen genes that may be relevant to the Chinese population, and the results indicated that PCDH9 was closely related to the prognosis of patients with MM, whereas RAC1 always played the opposite role in our natural bioproduct against melanoma study." (PMID 36387162, 2022). "PCDH9 and CCND1 (Cyclin D1) exhibited a positive correlation, whereas MMP2, MMP9, and RAC1 exhibited a negative correlation with both melanoma A375 and G361 cells." (PMID 36452505, 2022).
melanoma (continued). "Although the alteration of PCDH9 could influence CCND1 but not the cell cycle, which suggested it may affect melanoma cells by other mechanisms, such as SOCE combined melanoma cell migration, RAC1-dependent NADPH oxidase correlated with GTP-GDP switch." (PMID 36452505, 2022).
aneurysm (1 paper, 2022). Bulging or ballooning in an area of an artery secondary to arterial wall weakening. "In our other dataset (GSE54083), we were surprised to find that the expression of CDH11, SPARC, FN1, and FSTL1 in unruptured aneurysms was significantly increased, while WNT11, PCDH9, and GPC3 expression levels were relatively low." (PMID 34997174, 2022). "It was found that the expression levels of CDH11, SPARC, FN1, and FSTL1 genes in unruptured aneurysms were higher than those in healthy samples, while the expression levels of WNT11, PCDH9, and GPC3 in unruptured aneurysms were lower than those in healthy samples." (PMID 34997174, 2022).
Aqueductal stenosis (1 paper, 2024). Stenosis of the cerebral aqueduct (also known as the mesencephalic duct, aqueductus mesencephali, or aqueduct of Sylvius), which connects the third cerebral ventricle in the diencephalon to the fourth ventricle, which is between the pons and cerebellum. "Moreover, our study identifies the downregulation of specific genes, such as L1CAM, PCDH9, ISLR2, ADAMTSL2, and B4GAT1, which have been previously well characterized as playing an important role in congenital hydrocephalus and aqueductal stenosis." (PMID 39118132, 2024).
Ataxia (1 paper, 2020). Ataxia refers to impaired coordination of voluntary muscle movement. "Other genes are related to cytoskeleton remodeling, including Cdh4, Pcdh9, Dock5, Dock3 for the proprioceptors (mutation of Dock3 is known to results in ataxia) and Stom and Pdlim1 for mechanoreceptors, as well as ion channels (Asic1 and Kcnip2 for proprioceptive fate)." (PMID 32826903, 2020).
Cerebral ischemia (1 paper, 2023). Restriction of arterial blood supply to the brain associated with insufficient oxygenation to support the metabolic requirements of the tissue. "Compared to WT mice, Lrg1−/− mice exhibited increased protein levels of cell adhesion-related molecules, including Cldn11, Anxa2, Pcdh9, and Itgb5, in endothelial cells after cerebral ischemia‒reperfusion injury." (PMID 38037097, 2023). "Single-cell RNA sequencing analysis of WT and Lrg1−/− mouse brain tissues after cerebral ischemia‒reperfusion injury revealed that Lrg1 knockout enhances blood‒brain barrier (BBB) by upregulating claudin 11, integrin β5, protocadherin 9, and annexin A2." (PMID 38037097, 2023).
Cognitive impairment (1 paper, 2024). Abnormal cognition is characterized by deficits in thinking, reasoning, or remembering. "Considering the synapticlocalization of PCDH9, CDH13 and PCDH19, a mismatch in expression could alter the synaptic contactadhesion leading to network dysfunction and cognitive impairment, both of which arefeatures of PCDH19-CE pathology." (PMID 38629124, 2024).
colorectal cancer (1 paper, 2016). A primary or metastatic malignant neoplasm that affects the colon or rectum. "Additionally, the mutational frequency was >10% in 8 other TSGs in colorectal cancer: FAT4 (19%), TOPORS (15%), PPP2CB (13%), RASL11A (13%), PCDH9 (12%), PRDM2 (12%), LIFR (11%) and TGFBR2 (11%)." (PMID 26590405, 2016).
congenital hydrocephalus (1 paper, 2024). Hydrocephalus that is present at birth. "Moreover, downregulation of multiple proteins associated with congenital hydrocephalus (e.g., L1CAM, PCDH9, ISLR2, ADAMTSL2, and B4GAT1) points to a possible shared molecular foundation between congenital hydrocephalus and iNPH." (PMID 39118132, 2024).
COVID-19 (1 paper, 2021). A disease caused by infection with severe acute respiratory syndrome coronavirus 2. "Commonly altered host genes, such as PCDH9 and NCAM, related to immune protection were downregulated in all tested organ types and correlated with COVID-19 symptoms such as organ failure and reduced immune cell expansion." (PMID 34960687, 2021).
Dravet syndrome (1 paper, 2021). "These ASD genes included the Dravet syndrome gene SCN1A and the Timothy syndrome gene CACNA1C, but also GRIN2B, HTR2A, PCDH9, and other genes." (PMID 34188164, 2021).
Epileptic encephalopathy (1 paper, 2021). A condition in which epileptiform abnormalities are believed to contribute to the progressive disturbance in cerebral function. "Both CDH13 and PCDH9 have an intronic deletion and a duplication, respectively, and both have been associated to epileptic encephalopathy." (PMID 33557955, 2021).
glomerulosclerosis (1 paper, 2007). A hardening of the kidney glomerulus caused by scarring of the blood vessels. "For UAE, we observed strong association with ADAM23, a gene involved in the metalloproteinase family, which may be involved in the pathophysiology of glomerulosclerosis, and PCDH9, a gene that is a member of the cadherin superfamily." (PMID 17903292, 2007).
hairy cell leukemia (1 paper, 2007). Hairy cell leukemia (HCL) is a rare type of leukemia in which abnormal B-lymphocytes are present in the bone marrow, spleen and peripheral blood. "PCDH9 is predominantly expressed in brain, but is also expressed in hairy cell leukemia cells." (PMID 18466515, 2007).
lung carcinoma (1 paper, 2020). "Inhibition of Cyclin K with siRNA significantly reduced basal expression levels of Cyclin D1 and GNG3, while increasing expression levels of PCDH9, WNT9A and GNG7 in two different lung cancer cell lines." (PMID 33042275, 2020).
malignant glioma (1 paper, 2017). A grade III or grade IV glioma arising from the central nervous system. "The clinical prognosis of malignant gliomas is poor and PCDH9 down-regulation is strongly associated with its poor prognosis." (PMID 28055966, 2017).
myxofibrosarcoma (1 paper, 2025). A malignant fibroblastic neoplasm arising from the soft tissue. "In myxofibrosarcoma (MFS), a malignant soft tissue tumor, EVs with miR-1260b affect normal surrounding fibroblasts and enhance tumor growth through downregulation of the tumor suppressor gene protocadherin 9 (PCDH9)." (PMID 40243783, 2025).
tumor (34 papers, 2015 to 2026). "Previous studies have demonstrated that the loss of PCDH9 is associated with the proliferation, differentiation, and metastasis of tumor cells and predicts poor survival in different cancers." (PMID 36387162, 2022). "The loss of PCDH9 expression was associated with a higher histological grade of tumour and significantly shorter survival times." (PMID 28611294, 2017). "Moreover, circ_0084043 was discovered to regulate PCDH9 and other tumor-associated proteins through sponging miR-134-5p." (PMID 36387162, 2022). "The infiltrative nature of MFS could be explained by the inhibition of cell-cell adhesion between tumor and normal mesenchymal cells, which may be caused by PCDH9 suppression via tumor-derived EV-miR-1260b." (PMID 32523124, 2020). "Thus, the expression of PCDH9 is downregulated in tumours and the loss of its expression can be related to a more invasive phenotype." (PMID 28611294, 2017). "Compared to primary tumours, CSF cfDNA more frequently lost 13q regions containing PCDH9 and PCDH17 (members of the cadherin superfamily) and KLHL1, an actin binding protein with a role in cytoskeleton reorganisation." (PMID 37973922, 2023). "DPP7, CDR2L exhibited higher and UNC5C, RAB3B, SLC18A2, GPRASP1, PCDH9 exhibited lower expression in tumor tissues (P<0.05)." (PMID 37384293, 2023). "In some human diseases, PCDH9 is negatively correlated with the proliferation and apoptosis of tumor cells and is also a target of some anticancer molecules." (PMID 36421827, 2022). "Studies have revealed that amongst the 6 identified target genes, Dpp6 and Pcdh9 were Tumor suppressor genes (TSGs) and Avpr2, Cyp4a12b, Dpp6, Gria2, Pcdh9 and Tspan11 were key tumor-related transcripts that can regulate various pathways during carcinogenesis." (PMID 35263365, 2022). "We showed four representative images of PCDH9 IHC staining and further calculated the intensity of four stages of CCA tumor; meanwhile, the statistical results showed that the intensity of PCDH9 decreased with the increase of stage of CCA." (PMID 35903688, 2022). "To statistically clarify the intensity of PCDH9 in normal and tumor tissue, we collected 49 CCA samples." (PMID 35903688, 2022). "Non-cancerous liver cells and bile duct epithelium showed positive staining of PCDH9, significantly higher than that in tumor cells." (PMID 35903688, 2022). "The score of PCDH9 IHC staining in normal cells was 55.4 ± 25.0, significantly higher than that in tumor cells, 32.3 ± 30.4 (p = 0.0155)." (PMID 35903688, 2022). "PCDH9 is a target of β-elemene and displays an important role in predicting tumor recurrence in CCA patients." (PMID 35903688, 2022). "In contrast, two members of the protocadherin tumor suppressor family‐PCDH9 and PCDH10‐were down‐regulated in high B7‐H3 expressers." (PMID 34562306, 2021). "The results indicated that tumor-derived EV-miR-1260b promote local aggressiveness of MFS via the downregulation of PCDH9 in the peri-tumoral normal mesenchymal cells." (PMID 32523124, 2020). "In high-grade GBM, editing of miR589-3p decreases dramatically and unedited miR589-3p targets protocadherin 9 (PCDH9), a tumor suppressor protein, instead." (PMID 30619092, 2018). "PCDH9 expression is inversely correlated with tumour size, tumour differentiation, tumour invasion, lymph node metastasis, histological grade and patient survival." (PMID 29649113, 2018). "An in vivo study showed markedly reduced tumour growth with the expression of PCDH9 in comparison to the control." (PMID 29649113, 2018). "Based on previous vertebrate studies, PCDH9 may function as a tumor suppressor in echinoderm neuroectodermal tissues." (PMID 38124068, 2023). "Therefore, our results confirmed PCDH9 as a tumor suppressor and a predictor of patients’ survival time." (PMID 35903688, 2022).